ALB (albumin)
Diseases named in the same sentence as ALB in open-access papers (continued):
Sharing a sentence is not in itself a finding about the gene and the disease.
kidney disease (773 papers, 2005 to 2026). "This association extends to changes in known kidney disease markers, including baseline estimated glomerular filtration rate, urine albumin‐to‐creatinine ratio, and blood urea nitrogen levels." (PMID 40416952, 2025). "Filtered albumin in the glomerulus is reabsorbed into the proximal tubule, causing injury and contributing to kidney disease progression." (PMID 40527586, 2025). "CKD was categorized by estimated glomerular filtration rate < or ≥60 mL/min/1.73 m2, urine albumin-to-creatinine ratio < or ≥300 mg/g, or Kidney Disease Improving Global Outcomes (KDIGO) risk classification." (PMID 39211948, 2025). "These included older age, lower serum albumin, cardiovascular disease, cause of kidney disease, BMI, rate of eGFR decline and fewer nephrology visits prior to dialysis initiation." (PMID 39669010, 2024). "The cause, GFR, and albuminuria (CGA) classification severity, which is GFR- and urinary albumin-based severity combined with the cause of kidney disease, better reflects the prognosis." (PMID 38713253, 2024). "The decreased level of ALB has been proven to be associated with the severity of kidney diseases.Another protective gene BHMT is a novel prognostic biomarker for various diseases." (PMID 38961491, 2024). "Increasing age, baseline HbA1c, systolic BP and urinary albumin/creatinine ratio were also associated with kidney disease progression (p<0.05 for all)." (PMID 38902524, 2024). "Aldosterone excess has been linked to renal disease development with severe albuminuria, and aldosterone antagonism treatments reduce albumin excretion accompanied by increased serum creatinine." (PMID 39765751, 2024). "Unadjusted and adjusted hazard of (A) end-stage kidney disease: renal replacement therapy; (B) major adverse cardiovascular and cerebral events; and (C) all-cause death, by alkaline phosphatase-to-albumin ratio levels (continuous/categorical variable)." (PMID 37799589, 2023). "In this complex situation, it is obvious that a single marker such as urinary albumin cannot provide a clear indication on the cause of kidney disease." (PMID 37174905, 2023). "This association extends to alterations in known markers of kidney disease including baseline estimated glomerular filtration rate, urinary albumin-to-creatinine ratio, and blood urea nitrogen." (PMID 38107159, 2023). "For example, it has been shown that albumin deficiency poses benefits in the setting of kidney disease." (PMID 36979342, 2023). "A variety of markers associated with a more advanced stage of kidney disease were also observed in the highest score group (lower haemoglobin, albumin and calcium, higher phosphate, creatinine, and urine PCR)." (PMID 36048745, 2022). "For example, there was no biological variables such as relevant biomarkers of cystatin C, neutrophil gelatinase-associated lipocalin (NGAL, a new marker of kidney disease), etc., in addition to urine albumin-to-creatinine ratio (UACR)." (PMID 35314714, 2022). "As urinary albumin is a clinical risk factor for kidney disease development and progression and cardiovascular disease, the mechanism(s) mediating the presence and toxic effects of albuminuria, especially with respect to the PT, remain important questions." (PMID 35378997, 2022). "Currently, there are limited clinical studies focused on the association between serum albumin and the progression of kidney disease in IgAN patients with massive proteinuria." (PMID 35488221, 2022). "Transgenic mice that express wild-type or risk variant APOL1 from an albumin promoter were treated to cause kidney injury and evaluated for renal disease and pathology." (PMID 36279295, 2022). "Previous studies in children and adults have shown that urinary protein and albumin are associated with faster progression of some more severe kidney diseases." (PMID 35152314, 2022).
kidney disease (continued). "Glycosylation of albumin is increased with increasing serum glucose concentration and increases the susceptibility to diabetic complications including nephropathy." (PMID 35378997, 2022). "In the Danish study, ionized serum calcium was assessed and renal diseases were defined by diagnostic codes, whereas in the current study, albumin-corrected serum calcium was measured and CKD was identified by diagnosis codes or eGFR." (PMID 36389126, 2022). "It has long been known that rats develop kidney disease if they are caused to become hyperalbuminemic as a result of chronic administration of exogenous albumin." (PMID 35805070, 2022). "Decreased albumin concentrations are usually caused by acute inflammation, liver damage, starvation or cachexia, digestive disorders, or kidney diseases." (PMID 34566333, 2021). "Albuminuria is considered a hallmark for the progression of renal disease, and the increase in the urine urinary albumin excretion rate (UAE) in addition to the BUN level and KWI are all indicators for the development of DN in diabetic rats." (PMID 34694755, 2021). "The hypotension risk was significantly decreased based on the Kidney Disease Outcomes Quality Initiative definition; (15% with NS vs. 7% with albumin, p = 0.002)." (PMID 33407747, 2021). "Three subgroup definitions of low baseline kidney-risk were used: eGFR > 90 ml/min/1.73 m2; urinary albumin below detectable levels; and low risk according to Kidney Disease: Improving Global Outcomes (KDIGO) classification." (PMID 34407822, 2021). "The occurrence of renal disease deaths at a young age against a backdrop of national policies on annual albumin/creatinine ratio and eGFR checks and risk factor monitoring is also disturbing." (PMID 32451572, 2020). "Kidney diseases can lead to elevated levels of urinary albumin, while micro albuminuria is considered as a risk factor for hypertension." (PMID 32606332, 2020). "Urinary albumin-to-creatinine ratio (UCAR) is associated with various clinical outcomes such as kidney disease and cardiovascular disease." (PMID 31511532, 2019). "Increased levels of the urinary albumin-to-creatinine ratio (UACR) are associated with higher risk of kidney disease progression and cardiovascular events, but underlying mechanisms are incompletely understood." (PMID 31511532, 2019). "Variables such as age, primary renal disease, serum albumin and creatinine, treatment years stand as risk factors for functional impairment measured by KPS scores in HD patients." (PMID 29282123, 2017). "Several studies have reported that increases in these factors are associated with increased proteinuria and leakage of albumin and proteins in patients with renal diseases." (PMID 28420111, 2017). "Serum albumin has been associated with adverse vascular events in patients with cardiac and renal diseases." (PMID 23565300, 2013). "Various factors were analyzed as possible predictors of VRE colonization including: age, sex, underlying kidney disease, duration of dialysis, frequency of dialysis, serum albumin concentration and motility status." (PMID 17553129, 2007). "Additionally, 67% of GIH patients had a renal disorder and suffered from deficiency of vitamin D3 levels (73%) or albumin (86%)." (PMID 40863037, 2025). "Clinically, patients harboring monoallelic truncating mutations in the PODXL gene displayed the onset of renal disease during their third decade of life and experienced alterations on urinalysis, such as proteinuria and/or elevated serum creatinine and albumin levels." (PMID 40282423, 2025). "Consequently, deviations in albumin levels are often indicative of liver or kidney disorders, both of which are common complications associated with DFUs." (PMID 39409014, 2024). "However, after discovering the patient's nephrotic range proteinuria and low albumin, underlying renal disease was favored instead of cardiac involvement." (PMID 39092324, 2024).
kidney disease (continued). "The decreased level of albumin may be due to albumin loss in the urine in renal diseases/protein-losing gastropathy, decreased hepatic albumin synthesis, or protein malnutrition dysfunction." (PMID 37373829, 2023). "The urinary TF was suggested to be used as a diagnostic marker of early diagnosis of renal disease in Stage I of CKD cat since leakage of urinary TF in urine precedes leakage of urinary ALB, and their sensitivity and specificity were higher than those of plasma CR concentration." (PMID 36855344, 2023). "Increased levels of albumin in urine have been associated with cardiovascular and renal disease." (PMID 35265622, 2022). "ALB also decreased in renal diseases due to loss from the glomerulus." (PMID 33800652, 2021). "Even small amounts of albumin, i.e., microalbuminuria, are associated with increased morbidity and mortality and are therefore part of the chronic kidney disease staging according to the Kidney Disease: Improving Global Out- comes (KIDGO) guidelines." (PMID 33800255, 2021). "Importantly, we observed higher levels of U-albumin (p = 0.0005) and a significantly increased risk of renal disease in IgG anti-MDA-positive patients (OR = 2.1; p = 0.001)." (PMID 29482604, 2018). "Moreover, the assessment of the cognitive function subscale of the Kidney Disease Quality of Life showed the possibility to have an association between cognitive function and serum albumin concentration in CKD patients, including those undergoing HD." (PMID 29940017, 2018). "Moreover, urinary MCP-1 was associated with urinary oxidative stress and urinary albumin excretion, suggesting these patients are at increased risk of developing clinical kidney disease." (PMID 25142123, 2014). "Data on age, sex, diabetic status, race, cause of renal disease, hemoglobin, serum creatinine, serum calcium, serum phosphate, serum albumin, other co-morbidities, and our primary outcome (all-cause mortality) were obtained from the Manitoba Renal Program database." (PMID 24289833, 2013). "Notably, in response to HFD, urinary albumin excretion was significantly higher in Sirt3−/− than in WT mice, indicating that the lack of Sirt3 made mice more susceptible to developing early and more severe renal disease." (PMID 35955472, 2022). "However, if there is a problem with the reabsorption function, protein, albumin, blood, etc. may be seen in the urine, and waste materials accumulate in the body, causing uremia and kidney disease (nephropathy)." (PMID 36363953, 2022). "Therefore, an efficient dietary program controlling the protein and energy intake could improve the nutritional status of PD patients, keep the serum albumin at a steady state, slow renal disease progression, and decrease the risk of death." (PMID 34337034, 2021). "The results show that assessment of any renal outcome measure (whether serum albumin, urine PCR or remission) over time favoured the theory that renal disease activity was linked to the presence of anti-nucleosome and anti-dsDNA antibodies and not to anti-α-actinin antibodies." (PMID 19828047, 2009). "We were interested in whether both the p.R229Q and p.A242V variants might contribute to the risk of renal impairment in the general population by investigating whether these variants associate with increased urinary albumin/creatinine ratio, an early marker of renal disease." (PMID 18823551, 2008). "The link between the redox state of albumin and different health conditions has been underlined repeatedly, even in AS, T2DM, and kidney disease." (PMID 40722992, 2025). "Lower albumin levels can indicate liver or kidney disease, as well as inflammation or infections, and are a robust marker of frailty." (PMID 41372266, 2025). "Automated office BP measurements (AOBPM), 24-hour ambulatory BP measurements (24ABPM), TIS and Kidney Disease Improving Global Outcomes (KDIGO) > A2 levels of albumin to creatinine ratio (ACR) were measured at 3 (V3) and 12 (V12) months postpartum." (PMID 40281211, 2025).
kidney disease (continued). "Albuminuria is one of the most important markers of kidney disease, and it is often reported as albumin‐to‐creatinine ratio (UACR)." (PMID 40018982, 2025). "Electrochemical sensors with gold nanoparticle–modified electrodes have been used to quantify albumin redox states within minutes and have been validated using serum samples from patients with kidney disease." (PMID 41226246, 2025). "Human serum albumin(HSA) is a key biomarker for early detection of kidney disorders suchas microalbuminuria." (PMID 40727755, 2025). "Previously, we developed a quantitative measurement system for plasma oxidative stress using Cys34-cysteinylated albumin (oxidized albumin), which is also clinically useful as a biomarker for the progression of kidney diseases." (PMID 40527586, 2025). "SM was a significant biochemical covariate of urine albumin and the strongest lipid regressor for kidney disease in human T1D." (PMID 41347134, 2025). "Cats with kidney disease had more albumin in their urine, including those in the early stages when other test results appeared normal." (PMID 40723561, 2025). "Patients were categorized according to urinary albumin-to-creatinine ratio (UACR) elevation, estimated glomerular filtration rate (eGFR), or Kidney Disease: Improving Global Outcomes (KDIGO) risk classification." (PMID 40581865, 2025). "Inflammation reduces albumin synthesis via cytokines, while fluid overload (e.g., post-surgical patients or those with kidney disease) leads to albumin dilution due to plasma expansion." (PMID 40507204, 2025). "Kidney disease can be classified into six stages based on the kidney function index such as estimated glomerular filtration rate (eGFR) and urinary albumin-to-creatinine ratio (UACR)." (PMID 40581865, 2025). "CRP-to-albumin and neutrophil-percent-to-albumin ratios combine an inflammatory marker with a measure of nutritional status and have been studied in cardiovascular and kidney diseases." (PMID 41377914, 2025). "Patients from cluster 2 (SIRD) seemed older, with a higher risk of kidney disease (lowest GFR and highest values of urinary albumin/creatinine ratio)." (PMID 41003147, 2025). "When HSA leaks into urine due to kidney damage, it indicates the presence of microalbumin, a significant early warning sign of kidney disease." (PMID 39598335, 2024). "This calculator incorporates the kidney disease measures of estimated glomerular filtration rate and urine albumin to creatinine ratio to enhance the prediction for Cardiovascular Risk." (PMID 39399485, 2024). "Conditions like liver and kidney disease, as well as nutritional issues, can lead to low albumin levels." (PMID 39728311, 2024). "Urine albumin, high in kidney disease, predicts cardiovascular incidents and CNS white matter hyperintensity (WMH) burdens." (PMID 38260299, 2024). "The patient also showed a high urine albumin-creatinine ratio (47.5 mg/g) indicative of an early-stage kidney disease." (PMID 39464889, 2024). "The National Kidney Foundation Kidney Disease Outcomes Quality Initiative recommends the use of the urine microalbumin/creatinine ratio to assess urinary albumin excretion in patients with kidney disease." (PMID 38464361, 2024). "Elevated levels of VLDL and LDL are associated with glomerular lesions, interstitial fibrosis, and tubular cell damage, which can intensify the progression of kidney diseases and lead to albumin leakage into the urine." (PMID 39491271, 2024). "In multivariate approach limited to monotherapy patients, after correcting for age, underlying kidney disease, modality therapy duration, IDWG, serum parathyroid hormone, albumin, and blood hemoglobin, the effect of treatment choice remained significant." (PMID 38899176, 2024). "We initially selected Tg26 mice with significant albuminuria (>1 mg/mg urine albumin/creatinine) at 8 weeks of age to ensure likelihood of progressive of kidney disease." (PMID 39133556, 2024).
kidney disease (continued). "The groups were defined based on urine albumin levels, reflecting the potential progression of kidney disease." (PMID 38883096, 2024). "The largest number of participants reported a full confidence in knowing kidney disease stages, blood pressure targets and the importance of urine albumin–creatinine ratio testing." (PMID 39063457, 2024). "A limitation was that we were unable to investigate the association between air pollution and proteinuria, albuminuria, or albumin-creatinine ratio, which are also integral markers of renal disease." (PMID 39123230, 2024). "In future studies, the urinary levels of albumin should be assessed to better screen the onset of kidney disease." (PMID 37106960, 2023). "Previous studies have established the oxidative albumin as a vital mediator contributing to the initiation and development of renal diseases." (PMID 36671529, 2023). "Serum BUN, serum creatinine and CRP concentration were also significantly increased with a significant decrease in the serum in albumin concentration, which suggests the incidence of renal disease due to STZ administration." (PMID 36984840, 2023). "Moreover, PBUTs can bind to blood plasma proteins, such as human serum albumin, alter their conformational structure, block binding sites for other valuable endogenous or exogenous substances, and exacerbate the co-existing medical conditions associated with kidney disease." (PMID 37108613, 2023). "Previous reports showed the high level of urinary albumin-to-creatinine ratio in patients with PCOS.β2-microglobulin is another early and sensitive diagnostic indicator of kidney disease." (PMID 37008943, 2023). "The symptomatic HEV-4 patients with kidney diseases were older and had lower albumin levels and higher bilirubin and creatinine levels than the HEV-infected patients without kidney disease." (PMID 37242358, 2023). "Albumin reflects general health conditions, including nutritional status, and is affected by chronic liver disease, kidney disease, severe infections, and inflammation." (PMID 37654787, 2023). "Kidney disease was defined by the urinary albumin-to-creatinine ratio (ACR) and the estimated glomerular filtration rate (eGFR)." (PMID 38130638, 2023). "Reduction of serum albumin concentration is known to be one of the characteristic markers for both hepatic and renal diseases." (PMID 36984840, 2023). "The AG is affected by both measurable anions (albumin, phosphates) and unmeasurable anions, including those accumulated in kidney disease meltabilities, such as indoxyl, p-cresol and other uremic solutes." (PMID 37958263, 2023). "It has been documented that the level of albumin tends to decrease in various types of renal diseases." (PMID 38074142, 2023). "Albumin can undergo various post-translational modifications that can alter its physical characteristics, e.g., several liver and kidney diseases have been related to its oxidation state." (PMID 38069023, 2023). "In this study, we monitored urine output at three-day intervals, and measured albumin excretion rates as well as urinary NGAL levels in order to assess the progression of kidney disease." (PMID 37111431, 2023). "This study presents the development of a portable fluorometer with a smartphone application designed to facilitate the early screening of chronic kidney and renal diseases by enabling the sensitive detection of urinary albumin." (PMID 37754110, 2023). "In contrast, serum albumin (38.21 ± 5.48 g/L vs. 34.81 ± 8.64 g/L, p < 0.001) was lower in Type II kidney diseases than in Type I kidney diseases." (PMID 36849937, 2023). "Kidney disease is characterized by oxidative stress and inflammation, and in those with kidney disease, the presence of albumin allows for the progression of the disease to occur more quickly." (PMID 36979342, 2023).